TGFB1 (transforming growth factor beta 1)
Diseases named in the same sentence as TGFB1 in open-access papers (continued):
Sharing a sentence is not in itself a finding about the gene and the disease.
tumor (continued). "Additionally, this event could be due to the reduced expression of vimentin, evoked by siNDRG1 with TGFβ1 only in these types of cell lines, which is associated with tumor cell invasion and metastasis." (PMID 36594086, 2023). "TGFB1 encodes for one of the ligands of the transforming growth factor β protein family, which is known to inhibit host immunosurveillance and exert systemic immune suppression, and is known to play a role in tumor immune evasion and poor responses to cancer immunotherapy." (PMID 36345344, 2022). "Transforming growth factor β factors (TGFβ1, TGFβ2, and TGFβ3) are multi-tasking cytokines implicated in the regulation of a broad range of cellular functions and different biological processes i.e., embryogenesis, immune regulation, fibrosis-associated diseases, and tumor progression." (PMID 33672325, 2021). "Indeed, we also noticed that tumour-associated monocytes/macrophages could impair NK cells function through TGFβ1 to promote GC immune escape." (PMID 33602220, 2021). "Therefore, we have aimed to evaluate if Snail-1 and TGFβ1 genes expression correlate with one another in human PTC tissue samples or whether they are related to BRAFV600E mutation status or LNM tumor staging." (PMID 32825554, 2020). "In recent researches, it was reported that tumor-associated macrophages (TAMs) could secret TGFβ1 to promote LCSC properties by inducing EMT, and tumor-associated neutrophils (TANs) could secret TGFβ2 and BMP2, which induce miR-301b-3p and enhance stem cell characteristics in HCC." (PMID 33292618, 2020). "Moreover, signaling in MSCs via TNFα and TGFβ1 has been strongly associated with tumor progression." (PMID 28553282, 2017). "The up-regulated TGFB1 expression in malignant tumour cells and the up-regulated TGFB3 expression in premalignant tumour cells were very likely to have different, even opposite effects on the corresponding tumours, which also implicated the specific biology of different TGFβ isoforms." (PMID 26703884, 2015). "In this study, we addressed the specific function of tumor-produced TGF-β1 in tumor development by crossing mice carrying floxed/null alleles of Tgfb1 to the Mmtvcre deleter mouse strain in which cre recombinase directs deletion of the Tgfb1 allele from mammary epithelium." (PMID 22248703, 2011). "For example, PTEN and CASP8 act as tumor suppressors, whereas STAT3, MYC, EGFR, and TGFB1 are canonical oncogenic drivers implicated in cell cycle progression, stemness, and therapy resistance, particularly in triple-negative BC." (PMID 41596512, 2026). "Clinically, progressive or deceased DLBCL patients exhibited markedly higher levels of BAMBI and TGFB1 in tumour tissues compared with complete responders." (PMID 41492119, 2026). "Here, we observed higher TGFB1 and Tgfb1 expression in human tumor cluster 9 and mouse fibroblast cluster 8, respectively, which were both enriched populations in KPTN samples." (PMID 41480763, 2026). "In the GOYA cohort, high expression of BAMBI correlated with diminished CD4+ T cell enrichment in tumour tissues, a trend mirrored by TGFB1." (PMID 41492119, 2026). "We discovered that TBX3high tumor cells increase the secretion of TGFβ1, promoting CAF infiltration and creating an immunosuppressive microenvironment by inhibiting CD8+ T cell infiltration and their cancer-killing efficiency." (PMID 39897553, 2025). "For example, TGFB1 has shown both tumor-suppressive and tumor-promoting effects depending on stage and context, leading to inconsistent correlations with patient outcomes." (PMID 40650134, 2025). "It is demonstrated by our study that TGFβ-1 and CXCR4 are critical factors in the tumorigenesis of BC and their inhibition shows interference with tumor-associated pathways in a synergistic way." (PMID 41348904, 2025). "Transforming growth factor beta 1 (TGFβ1) stored in platelet α-granules is an important initiator of tumor cell proliferation." (PMID 40723273, 2025).
tumor (continued). "Genes downregulated by both agents included those corresponding to stem cell signatures, SMARCA4 target genes, EMT, and MYC targets, tumor invasiveness and TGFB1 signatures." (PMID 41279405, 2025). "Significant upregulation of Tgfb1, Tgfb3, and Vegfa was observed in 4T1 tumor tissues post‐irradiation." (PMID 40470716, 2025). "UCA1 promotes tumor energy metabolism by increasing TGFβ1 expression, which enhances glucose uptake, lactate production, and ATP generation, supporting tumor cell survival and growth." (PMID 41437175, 2025). "We found that TBX3high tumor cells increased the secretion of TGFβ1, thereby promoting infiltration of CAFs and inducing an immunosuppressive microenvironment in BLCA." (PMID 39897553, 2025). "We knocked down Tgfbr2 on Kras mutant LUAD cell line (LKR) by in vitro and found high expression of TGFβ1 in tumour cells and supernatant." (PMID 41431249, 2025). "These downstream effectors translocate to the nucleus and promote the transcriptional upregulation of TGFβ1, fostering an immunosuppressive tumor microenvironment through Treg cell recruitment." (PMID 40725832, 2025). "In NSCLC, CXCR7 overexpression in tumor cells promoted primary tumor growth and metastasis in A549 cells, but its silencing inhibited TGFβ1-induced migration, invasion, EMT, and reduced stem-like properties and chemoresistance." (PMID 41149503, 2025). "The potential of these compounds to target complex diseases linked to TGFβ1 and endoglin motivates their use in combination with PDT, with the aim of enhancing treatment efficacy by mitigating tumor resistance 17-19." (PMID 40384860, 2025). "This supports a reinforcing feedback mechanism was involved PLVAP and TGFβ1, as well as functional divergence between tumour‐ and tip‐cell‐derived TGFβ1." (PMID 41431249, 2025). "In order to assess the role of TGF-β1 specifically produced by tumor cells in CDDP-Eri plus anti–PD-L1 resistance, we developed a Tgfb1–/– 4T1 cell line." (PMID 40590231, 2025). "Many studies have pointed at TGFβ1 in the tumor microenvironment as one of the possible culprits of resistance to different therapies in various types of cancer." (PMID 40384860, 2025). "In this study, we model a situation in which resistance arises prior to treatment due to features of the tumor microenvironment, specifically high levels of TGFβ1 secreted by CAFs." (PMID 40384860, 2025). "This subtype has been designated the mesenchymal cluster or normal-like/claudin-low and overexpresses genes associated with tumor invasive and aggressive features such as up-regulation of VIM, TGFB1 and SERPINE1/2 and cancer stemness such as CD44 expression." (PMID 38819630, 2025). "At the same time, TGFβ1 plays a dual role in cancer development 8 and can transition from tumor suppressor to tumor enhancer in the later stages of cancer." (PMID 39991579, 2025). "Transforming growth factor β1 (Tgfβ1), abundant in the tumor microenvironment (TME), regulates cellular differentiation via the classical Smad2/3 pathway, yet paradoxically fails to drive MDSC maturation." (PMID 41360769, 2025). "This is also consistent with the fact that ThPOK regulates TGFB1 mRNA and TGFβ signaling pathways which play a critical role in tumor formation, progression and metastasis." (PMID 41231242, 2025). "This spatial understanding of tumour–immune cell interactions underscores the potential of TGFβ1 and PD‐L1 pathway inhibition to prevent HCC recurrence by disrupting immune‐evasion mechanisms in MRD." (PMID 40677104, 2025). "NPC2 positive macrophages secrete TNF and TGFB1 that act on tumor cells, thereby enhancing the proliferation of tumor cells." (PMID 40620715, 2025).
tumor (continued). "Immunosuppressive macrophages further contribute to tumor progression by promoting angiogenesis through direct interactions between transforming growth factor-beta 1 (TGF-β1) and integrin αvβ3, highly expressed on angiogenic endothelial cells." (PMID 40427130, 2025). "The upregulation of key mediators such as TNF, IL1A/B, INFG, INFA2, and TGFB1 in tumor-educated immune cells suggests a shift toward a pro-inflammatory yet immunosuppressive phenotype." (PMID 41514627, 2025). "TGFB1 is known to transition from a tumor suppressor in early tumorigenesis to a tumor promoter in advanced stages by inducing epithelial–mesenchymal transition (EMT), fibrosis, and immune evasion." (PMID 41465262, 2025). "Concurrently, RSV upregulates miR-663, a tumor-suppressor miRNA that specifically targets TGFβ1 transcripts." (PMID 40969596, 2025). "Here, a DNA origami-based framework functionalized with anti-TGFβ1 aptamers is developed to act as a captor for efficient TGFβ1 sequestration and fast clearance, thereby improving anti-tumor immunity." (PMID 40641297, 2025). "MAP3K1, PPM1D, LMTK3, and TGFB1 levels were significantly elevated across all tumor subtypes, with the highest concentrations consistently observed in TNBC (e.g., TGFB1: 544.92 ± 29.81 pg/mL; MAP3K1: 15.44 ± 0.56 ng/mL)." (PMID 41465262, 2025). "Our study provided TGFb1 as a marker for healing process in the tumor bed after PN and paved the way for further investigations of the therapeutic uses of TGFb1 post-PN." (PMID 40182573, 2025). "Tumour‐secreted TGFβ1 upregulated PLVAP in endothelial cells, promoting angiogenesis and tumour invasion." (PMID 41431249, 2025). "We further validated the mRNA expression changes of Tgfb1 and Vegfa in various tumor cells after irradiation using qRT‐PCR." (PMID 40470716, 2025). "This intricate network highlights the dual role of TGFβ1 in tumor suppression and therapy resistance, emphasizing its potential as a therapeutic target in cancer treatment strategies, including PDT." (PMID 40384860, 2025). "In comparison to non-tumor samples, it was observed that the protein levels of TGFβ-1, IL19, CXCR4, BMP1, VCAN, and WNT2 were significantly enhanced in several tumor samples." (PMID 41348904, 2025). "In 6 of our cell lines, as in our mouse models, we observed induction of Tgfb1 gene expression when the tumor cells were treated with CDDP or its combination with Eri, irrespective of the transcriptomic subtype of TNBC." (PMID 40590231, 2025). "TGFB1 gene acts as a tumor suppressor by activating cell apoptosis and reducing the expression of genes encoding vascular endothelial growth factor." (PMID 41305721, 2025). "Via RNA sequencing, it was found that platelets release TGFβ1 and alter the signaling pathway in tumor cells." (PMID 40723273, 2025). "TGFβ1 is a cytokine known to suppress tumor formation in some contexts and promote tumor progression in others." (PMID 41155247, 2025). "The released substances changed the makeup of the tumor stroma, making cancer-associated fibroblasts (CAFs) resistant to GEM and increasing the production of TGFβ1." (PMID 40270972, 2025). "For instance, in glioblastoma, Zman-seq revealed that within 24 hours of tumor infiltration, cytotoxic natural killer (NK) cells transitioned to a dysfunctional state regulated by TGFβ1 signaling." (PMID 41425696, 2025). "Here we present new humanized isogenic models for G3MB driven by MYC amplification and overexpression of TGFβ pathway effectors ACVR2A, TGFβR1, and TGFβ1 that recapitulate the human tumor type." (PMID 41415380, 2025). "In the tumor tissue, TGFβ-1 expressions were inhibited in all combination treatment groups when compared with the rAd.sT.GM group, suggesting a stronger blockade of TGFβ-1 mediated pro-tumorigenic signaling in the tumor microenvironment by the combinations." (PMID 40104170, 2025).
tumor (continued). "These CAR-NK cells demonstrate strong anti-tumour effects in both spheroid cultures and in vivo models, offering a promising strategy to overcome TGFβ1-mediated immune suppression and improve cancer immunotherapy." (PMID 40650066, 2025). "Similar to before, LY96 positive macrophages secrete TNF and TGFB1 that act on tumor cells, thereby enhancing tumor cell proliferation." (PMID 40620715, 2025). "Analyses of samples demonstrated that PCLAF and TGFB1 expressions were much higher in tumor (T) than in adjacent normal (N) tissues." (PMID 41035818, 2025). "The results showed that RT promoted Tgfb1 mRNA expression in 4T1, CT26, H22, and GL261 tumor cells, which was similar to TGF‐β1 levels in the supernatants of 4T1, CT26, H22, and GL261 cells measured by ELISA." (PMID 40470716, 2025). "The main sources of CAFs arise from normal fibroblasts within the tumor microenvironment, with growth factors like transforming growth factor-beta 1 (TGF-B1) and stromal cell derived factor-1 (SDF1) facilitating this transformation." (PMID 40868227, 2025). "These cells were either treated with GEM, a common chemotherapeutic drug for PDAC, stimulated with TGFB1, a factor which is secreted from the tumor stroma to drive the desmoplasmic reaction, which is predominant in PDAC, or both." (PMID 41209344, 2025). "To analyze the molecular processes in tumor cells and CAFs, we applied scRNA-seq to dissociated H2228 and H3122 tumor spheroids either mono-cultured or co-cultured with TGFβ1-activated FB2 fibroblasts." (PMID 40524253, 2025). "Exosomal miRNAs, such as miR-34a and miR-1246, can activate TGFβ1 signaling, leading to increased ROS production and fibroblast-mediated tumor progression." (PMID 40427384, 2025). "For example, the upregulation of cathepsin B induced by alterations in the TGFβ-1 signaling pathway contributes to the carcinogenic potential of tumor cells." (PMID 40427636, 2025). "TGFb1 is an important tumor suppressor and its tumor function is considered an important tumor suppressor." (PMID 40822022, 2025). "TGFB1 is essential for invasive growth and proliferation in GC tumor cells, such as GCTM-1 GC cell line, in which TGFB1 induces enhanced expression of matrix metalloproteinase 9 (MMP9) and PLAU in tumor cells." (PMID 40075643, 2025). "These interactions, primarily mediated by CXCL12 and transforming growth factor β1 (TGFB1), collectively facilitate tumor growth and progression." (PMID 40170852, 2025). "Interleukin (IL)-10 and TGFβ1 are potent immunosuppressive cytokines in the tumor microenvironment (TME) that inhibit cancer killing by bispecific antibodies, yet they did not reduce GlyTR1 killing activity individually or combined." (PMID 41005308, 2025). "During early tumorigenesis, Tgfβ1 exerts tumor-suppressive effects by inducing apoptosis, differentiation, and cell-cycle arrest through modulation of key genes such as p15, p21, c-myc, inhibitor of DNA binding (ID1/2/3), and DAP kinase." (PMID 41360769, 2025). "TGFβ1 plays a dual role in tumor progression by promoting both oxidative stress and immune suppression." (PMID 40427384, 2025). "In the TCGA database, compared with normal tissues of GC, the expression level of TGFβ1 in tumor samples was significantly increased, the same results were also observed in paired sample data of pan cancer data." (PMID 39991579, 2025). "The activation of proliferative signals suggests that TGFβ1+ Treg not only increase in number but also expand their functional influence within the tumor microenvironment." (PMID 40891683, 2025). "Overall, the top four checkpoint genes associated with KLF4 and correlated with a tumor inhibitory effect in several tumors were C10orf54, CD274, IL10, and TGFB1." (PMID 40299916, 2025). "When TGFB1 expression is up-regulated in tumor cells, PCLAF protein expression in CAFs is reduced, and their invasion and migration abilities are inhibited." (PMID 41035818, 2025).
tumor (continued). "Studies in non-tumor cells have shown that ADAMTS6 can activate the latent transforming growth factor beta 1 (TGF-β1) and downstream SMAD2/3 pathway, whose role in EMT has been demonstrated in numerous studies." (PMID 41465277, 2025). "Tumor cells exhibited strong interactions with CAFs, primarily involving TGFB1/2 (Tumor) - TGFBR1/2 (CAF) and various collagen-integrin pairs, particularly enriched in MIP and ACI regions." (PMID 40918135, 2025). "We demonstrate that miR-675 expression inhibits primary tumor growth and metastasis by targeting TGFβ1, suppressing epithelial to mesenchymal transition (EMT), and attenuating the TGFβ signaling pathway." (PMID 39744561, 2025). "Upregulation of tumor cells PD‐L1 is considered a novel mechanism of TGFβ1‐induced immunosuppression in NSCLC." (PMID 39083441, 2025). "Once cancer spreads to the bones, TGFB1 plays a pleiotropic role in the regulation of the tumor microenvironment by stimulating PCa cell proliferation and migration and inducing bone remodeling and angiogenesis." (PMID 40122809, 2025). "TGFβ1 secreted by CAFs present in the tumor microenvironment induces resistance to different therapies, in particular to PDT in cSCC cells as it was previously demonstrated by our group 23." (PMID 40384860, 2025). "Multiple pieces of evidence suggest that TGFβ1 intervenes in the tumor microenvironment, immune cells and GC prognosis." (PMID 39991579, 2025). "The tumor uptake on [68Ga]Ga‐Trivehexin distinctly correlated with TGFβ1 and Ki‐67, except for integrin αvβ6." (PMID 40899568, 2025). "Functionally, overexpression of Linc-pint suppresses PDAC cell proliferation, and this tumor-inhibitory effect is synergistically enhanced by TGFβ1." (PMID 41437175, 2025). "In the context of its tumor suppressor role, TGFβ1 signaling is able to induce the expression of P21, a critical protein that regulates the cell cycle by inhibiting cyclin-dependent kinases." (PMID 40384860, 2025). "In vivo models confirmed that the overexpression of tricellulin facilitated tumor growth and activated the TGFb1/ SMAD2/3 pathway in CRC." (PMID 40291908, 2025). "Excessive immune activation further recruits M2 macrophages, which enhance PD-L1-mediated immunosuppression via IL-10 and TGFβ1, thus reducing cytotoxic T-cell tumor infiltration and promoting tumor recurrence." (PMID 41006707, 2025). "In contrast, our data in LUAD uncover a TGFβ1‐centric mechanism whereby Tgfbr2‐deficient tumour cells secrete TGFβ1 to induce PLVAP in tip‐like ECs, driving tumour invasiveness." (PMID 41431249, 2025). "TGFb1 levels in urine after PN are related to the amount of devitalized renal parenchyma due to renorrhaphy of tumor bed and can predict unfavorable renal function post-PN." (PMID 40182573, 2025). "TGFB1 is recognized for its dual function in cancer, serving as a tumor suppressor during the initial stages and as a promoter of tumor progression in later stages." (PMID 40458414, 2025). "We next further ascertain the predictive potential of Tgfβ1 for MO-/PMN-MDSC ratio across various tumor types." (PMID 41360769, 2025). "It is pertinent for us to analyze the function of Tgfβ1 in tumor MDSC, a growth factor abundant in tumors and possessing the ability to promote cell differentiation, which did not help the differentiation of MDSC into mature cells." (PMID 41360769, 2025). "The pseudotime analysis further validated this trend, showing a significant increase in TGFβ1+ Tregs during the late tumor grade, while NCF1+ Tregs and proliferative Tregs decreased, a pattern opposite to that observed in the early pseudotime grades." (PMID 40891683, 2025). "When TGFB1 is upregulated, it can suppress the body's natural anti - tumor defenses, thus facilitating tumorigenesis 16-18." (PMID 40861819, 2025). "Meanwhile, our findings indicate that during the initial phase of tumour infiltration, a subset of tip cells expressed TGFβ1, which promoted tumour cell invasiveness." (PMID 41431249, 2025).